REN (renin)
Diseases named in the same sentence as REN in open-access papers (continued):
Sharing a sentence is not in itself a finding about the gene and the disease.
nephrosclerosis (6 papers, 2013 to 2022). Hardening of the kidney due to infiltration by fibrous connective tissue (fibrosis), usually caused by renovascular diseases or chronic hypertension. "Some authors have also shown that plasma renin activity and renin responsiveness decrease with age, possibly due to the effect of age-associated nephrosclerosis." (PMID 24391595, 2013). "This article explores the renin-angiotensin-aldosterone system with plasminogen activator-inhibitor-1 interaction and the potential significance of these interactions in the pathogenesis of progressive renal disease and remodeling of renal sclerosis." (PMID 32728402, 2020). "This is relevant to the development of nephrosclerosis, as PGE2 contributes significantly to kidney disease, as it is involved in albuminuria, growth/fibrosis, and the activation of the renin–angiotensin–aldosterone system (RAAS)." (PMID 34442416, 2021).
non-small cell lung carcinoma (6 papers, 2015 to 2025). A group of at least three distinct histological types of lung cancer, including non-small cell squamous cell carcinoma, adenocarcinoma, and large cell carcinoma. "Here we suggest that polymorphic variants in genes coding for renin-angiotensin system might play a role in Non-Small Cell Lung Cancer progression." (PMID 33353148, 2020). "The aim of this study is to determine whether renin-angiotensin system blockers (RASBs), which include angiotensin-converting enzyme inhibitors (ACEIs) and angiotensin-2 receptor 1 blockers (ARBs), improve the overall survival (OS) of patients with metastatic non-small cell lung cancer (NSCLC)." (PMID 26039117, 2015).
orthostatic hypotension (6 papers, 2015 to 2025). Sudden fall of the blood pressure of at least 20/10 mm Hg when a person stands up. "Barring mineralocorticoid receptor antagonists, most classes of guideline-directed medical therapy including renin-angiotensin-aldosterone inhibitors and beta blockers are avoided in CA due to intolerance and the risk of potentiating orthostatic hypotension." (PMID 39618657, 2024). "Our data demonstrate that higher resting levels of renin predicts maximal decrease in SBP occurring first after the initial 3min of HUT, which suggests an elevated renin activity to predict delayed orthostatic hypotension." (PMID 26053073, 2015). "Renin-angiotensin system inhibitors are poorly tolerated due to orthostatic hypotension." (PMID 38610755, 2024). "We have observed that resting CT-proET-1, CT-proAVP, MR-proANP, and renin are elevated in patients with orthostatic hypotension, of these, two latter in the delayed form only, while BP fall on standing is associated with a significant release of vasopressin and epinephrine." (PMID 26053073, 2015).
pancreatic cancer (6 papers, 2010 to 2025). "Equally, Myseq-621 (zma-miR169a-3p) is associated with renin secretion, and its inhibition improved the clinical outcome of advanced pancreatic cancer." (PMID 32292571, 2020). "(Pro)renin was found to be expressed by pancreatic cancer stromal cells and the endothelium of pancreatic tissue vasculature." (PMID 37623681, 2023).
pulmonary diseases (6 papers, 2015 to 2024). "The renin–angiotensin–aldosterone system (RAAS) plays a significant role in various pulmonary diseases." (PMID 38200555, 2024). "The renin-angiotensin system (RAS) plays a key role in maintaining blood pressure but is also often involved in lung disease." (PMID 35308222, 2022). "The renin–angiotensin–aldosterone system (RAAS) is an important mediator of cardiac and pulmonary disease." (PMID 37106412, 2023). "In the lung, the chronic activation of the renin-angiotensin-aldosterone system (RAAS), which regulates cell proliferation, immune-inflammatory response, hypoxia, and angiogenesis, contributes to lung injury and different pulmonary diseases." (PMID 38464782, 2024). "The renin-angiotensin-aldosterone (RAAS) and kallikrein-kinin (KKS) endocrine systems are involved in the pathophysiology of cardiovascular diseases and have been found to impact lung diseases." (PMID 26113123, 2015).
pulmonary edema (6 papers, 2020 to 2025). Accumulation of fluid in the lung tissues causing disturbance of the gas exchange that may lead to respiratory failure. "Furthermore, hACE2-R overexpression during the infection can deregulate these systems, causing acute inflammatory pulmonary edema (kinin-kalicrein system), cardiovascular instability (renin-angiotensin system) and thromboembolism (coagulation system)." (PMID 33919537, 2021). "The occurrence of pulmonary edema indicated activation of the apoptotic FasL/Fas signaling pathway, activation of the renin-angiotensin signaling pathway, and activation of the NF-κB signaling pathway." (PMID 32286320, 2020).
renal hypertension (6 papers, 2014 to 2022). Hypertension caused by the kidney's hormonal response to narrowing or occlusion of the renal arteries. "Then, synthetic ACEIs such as ramipril, lisinopril, perindopril, enalapril, and captopril were developed and have been successively used clinically as antihypertensive drugs, especially for the treatment of renal hypertension (high renin/high aldosterone)." (PMID 36235721, 2022). "These included serum markers, such as SCr, BUN, cystatin C, GFR, and renin, a marker related to renal hypertension." (PMID 33805740, 2021). "Later, it was found that homologous renin could be chemically altered to make it antigenic; in dogs with renal hypertension, subcutaneous administration of acetylated dog renin three times a week for 10 weeks was shown to progressively reduce blood pressure to the normotensive level." (PMID 31485348, 2019). "The pathological mechanism of renal hypertension is complex, including activation of the sympathetic nervous system (SNS) and renin-angiotensin-aldosterone system (RAAS), oxidative stress, increased endothelin-1 (ET-1), and inflammation." (PMID 37675019, 2022). "Similarly, although the SBP and DBP were consistently more elevated in the preterm-born group, the serum levels of renin, a biomarker of renal hypertension, did not significantly differ." (PMID 33805740, 2021).
sarcoidosis (6 papers, 2021 to 2024). Sarcoidosis is a multisystemic disorder of unknown cause characterized by the formation of immune granulomas in involved organs. "In sarcoidosis, it was suggested that SARS-CoV-2 might trigger the formation of noncaseating granulomas via the renin–angiotensin system and the innate immune system." (PMID 34944099, 2021).
Ventricular arrhythmia (6 papers, 2014 to 2024). "The use of renin-angiotensin-aldosterone system antagonists is associated with a reduced incidence of ventricular arrhythmias." (PMID 26095682, 2015). "Furthermore, inhibition of renin release from mast cells prevented activation of the renin–angiotensin system (RAS), reduced infarct size, and alleviated ventricular arrhythmias." (PMID 33996944, 2021). "In summary, in this post hoc analysis, dapagliflozin, compared with placebo, reduced the incidence of investigator-reported (but not adjudicated) ventricular arrhythmias in patients with HFrEF, most of whom were treated with a renin–angiotensin system blocker, beta-blocker, and an MRA as well." (PMID 34448003, 2021).
adrenal crisis (5 papers, 2015 to 2024). "Deficiency of cortisol level (secondary AI) with intact renin-angiotensin-aldosterone system can cause adrenal crisis if it is severe or patients are in acute illness." (PMID 25574364, 2015). "Secondary adrenal insufficiency (SAI) often presents with only glucocorticoid deficiency because aldosterone production, which is controlled by the renin angiotensin system, is usually intact, and rarely presents with an adrenal crisis." (PMID 37238296, 2023). "Total serum levels of tryptophan, kynurenine, and 3-hydroxykynurenine, kynurenine to tryptophan ratio, aldosterone, renin and metanephrines in patients on the lower dose hydrocortisone (0.2-0.3 mg/kg/day) with or without a history of an adrenal crisis." (PMID 35518935, 2022).
Cachexia (5 papers, 2017 to 2024). Severe weight loss, wasting of muscle, loss of appetite, and general debility related to a chronic disease. "Based on our previous literature review, cachexia is a complex syndrome connected with several signaling pathways, including TGF-β signaling activation, PI3K/Akt/mTOR signaling, the renin–angiotensin–aldosterone system (RAAS) pathway, myostatin and activin signaling, and the hypoxia/HIF-1 pathway." (PMID 38203330, 2023).
cardiac arrest (5 papers, 2015 to 2025). Cessation of breathing and/or cardiac function. "Possible upregulation of the renin-angiotensin-aldosterone system due to physiologic stress and cardiac arrest leads to greater sodium reabsorption and potassium excretion, which may provide a partial explanation for the electrolyte values." (PMID 40831821, 2025). "Our study explored whether sildenafil protects against I/R-induced damage in a porcine cardiac arrest and resuscitation (CAR) model via modulating the renin-angiotensin system." (PMID 26569234, 2015).
cytomegalovirus infection (5 papers, 2009 to 2025). A herpesvirus infection caused by Cytomegalovirus. "Expression of renin in mouse and human cells after persistent cytomegalovirus infection caused an increase of arterial blood pressure." (PMID 32609737, 2020). "Accordingly, we hypothesized that HCMV infection increases the risk of EH by regulating inflammatory and oxidative responses, the renin–angiotensin system (RAS), endothelial function, and DNA methylation." (PMID 29752343, 2018). "A persistent CMV infection of EC and an increased pro-inflammatory cytokine expression, including renin and AngII, may underlie the molecular mechanism by which CMV infection induced an increase of blood pressure." (PMID 19436702, 2009). "An in vivo experimental study showed that CMV infection increased arterial pressure, and stimulated renin expression in a dose-dependent manner in kidney cells and vascular endothelial cells, as well as increased Ang II levels in blood and arterial tissues." (PMID 29752343, 2018). "Specifically, we have identified that CMV infection induced expression of renin in an infection dose responsive manner in mouse renal cells and in human vascular endothelial cells." (PMID 19436702, 2009). "Further studies show that CMV infection induces renin and angiotensin II (Ang II) expression in blood and in vessel cells, in a persistent infection manner." (PMID 19436702, 2009). "Specifically, HCMV infection is known to induce renin and angiotensin II (Ang II) expression in a dose-dependent manner in human vascular endothelial cells and increase arterial blood pressure (BP) by stimulating renin and cytokine production in mice." (PMID 29752343, 2018). "Additionally, we find that besides stimulating expression of inflammatory cytokines reported to increase blood pressure, CMV infection stimulated expression of renin, the first component of RAS, in both kidney cells and EC, in a dose-dependent manner." (PMID 19436702, 2009). "Expression of viral genes and viral persistent infection of blood vessel endothelial cells resulting in an increased expression of inflammatory cytokines, including renin and Ang II, may underpin the molecular mechanism by which CMV infection induces an increase in blood pressure." (PMID 19436702, 2009). "The present study supports that HCMV infection plays an important role in EH pathogenesis through increased TNF-α and 8-OHDG levels, and decreased eNOS and renin levels." (PMID 29752343, 2018). "Since renin generated in kidney cells is the key component of circulatory RAS, our data suggest that CMV infection stimulated RAS activity and contributed to an increase of blood pressure in vivo." (PMID 19436702, 2009). "We determined renin expression in both mouse and human cells after CMV infection, and find that CMV infection increased renin expression in cells in a MOI dependent manner." (PMID 19436702, 2009). "Thus, CMV infection did not contribute to the mouse weight gain, but caused an increase of blood pressure apparently via a change in expression of cellular genes, the over expression of inflammatory cytokines, renin and Ang II in the vascular system." (PMID 19436702, 2009). "Surprisingly, we found that HCMV infection significantly reduced renin-mediated EH incidence and independent negative correlations were observed between renin and HCMV antibody titer and BP in hypertensive subjects." (PMID 29752343, 2018). "Notably, patients with EH, particularly those with HCMV infection, exhibited a marked increase in tumor necrosis factor-α (TNF-α) and 8-hydroxy-2-deoxyguanosine (8-OHDG) levels, but a decrease in endothelial nitric oxide synthase (eNOS) and renin levels." (PMID 29752343, 2018).
electrolyte disorders (5 papers, 2015 to 2025). "Moreover, plasma aldosterone and renin, important determinants of electrolyte disorders were not measured in the study." (PMID 26298426, 2016).
hypertriglyceridemia (5 papers, 2013 to 2024). A laboratory test result indicating elevated triglyceride concentration in the blood. "Neither patient had a history of infantile cardiomyopathy but both had a history of severe hypertriglyceridaemia in teenage years (>50 mmol/l) with pancreatitis and raised plasma renin (>3000 ng/L) when normotensive." (PMID 26104972, 2015).
Hypocalcemia (5 papers, 2010 to 2025). An abnormally decreased calcium concentration in the blood. "In addition, hypocalcemia leads to the activation of the renin-angiotensin-aldosterone system directly or indirectly by increasing PTH production." (PMID 40290310, 2025). "In addition, hypocalcemia can stimulate renin release, resulting in elevated angiotensin II and aldosterone levels, which promote sodium retention and vascular constriction." (PMID 40170590, 2025). "In addition, they also found that renin up-regulation was evident prior to hypocalcaemia suggesting that regulation of renin by 1,25(OH)2D3 is independent of serum calcium." (PMID 23355878, 2013).
infarction (5 papers, 2011 to 2024). A localised pathological necrosis of tissue resulting from obstruction of the blood supply usually by a thrombus, an embolus, or vascular torsion. "Apoptotic cardiomyocyte loss after infarction is also known to be variable, and its severity and extent can be modulated by several pathophysiological mechanisms and variables, such as the renin-angiotensin-aldosterone system or adrenergic stimulation." (PMID 23441146, 2013). "It was observed that vitamin D has a significant impact on the renin–angiotensin–aldosterone system, which may be crucial in the early phase of post-infarction heart remodeling." (PMID 39728467, 2024).
influenza (5 papers, 2017 to 2025). An acute viral infection of the respiratory tract, occurring in isolated cases, in epidemics, or in pandemics; it is caused by serologically different strains of viruses (influenzaviruses) designated A, B, and C, has a 3-day incubation period, and usually lasts for 3 to 10 days. "Previous studies have shown that in critically ill patients (including those with influenza), renin activity and angiotensin II levels correlate with tissue injury, disease severity, and outcome." (PMID 36418458, 2022).
intrauterine growth restriction (5 papers, 2019 to 2026). "The elevated NT-proBNP levels in sIUGR premature twins may be associated with cardiac overload resulting from renin-angiotensin system activation, hypoxemia due to reduced blood volume, and intrauterine growth restriction." (PMID 41602321, 2026). "Different models of developmental origins of adult disease are based on the exposure to low protein diet, excess of glucocorticoids, induced intrauterine growth restriction and postnatal blockade of the renin-angiotensin system." (PMID 32982785, 2020).
iron deficiency (5 papers, 2020 to 2025). "Magnesium deficiency exacerbates oxidative stress by promoting the accumulation of reactive oxygen species (ROS), primarily through mitochondrial dysfunction, disrupted calcium homeostasis, and activation of the renin–angiotensin–aldosterone system." (PMID 41010443, 2025). "This review article has discussed the multifactorial pathophysiology, including iron deficiency, longstanding inflammation, abnormal levels of human erythropoietin (Epo), and the abnormal activation of the renin-angiotensin-aldosterone system (RAAS) being the most significant." (PMID 36017290, 2022).
kidney stone (5 papers, 2019 to 2025). "3Excess body weight can cause an increase in the amount of sodium that is reabsorbed by the kidneys, thus activating the renin-angiotensin and sympathetic nervous systems, which in turn leads to an increased prevalence of nephrolithiasis." (PMID 37284217, 2023). "To further validate the ameliorative role of FMT in kidney stone-induced damage in hyperoxaluric rats, we performed immunohistochemical staining to evaluate the protein levels of renin, ACE, and OPN." (PMID 37313343, 2023).
mineralocorticoid insufficiency (5 papers, 2021 to 2025). "Additional laboratory testing should include electrolyte panel, aldosterone, and plasma renin activity if mineralocorticoid insufficiency is suspected (e.g., dizziness, orthostatic hypotension, salt craving)." (PMID 39335112, 2024). "Renin elevation may precede overt electrolyte abnormalities and is an early marker of mineralocorticoid insufficiency in salt-wasting forms of CAH." (PMID 40909093, 2025).
mood disorder (5 papers, 2011 to 2024). A cognitive disorder a disturbance in which the person's mood is hypothesized to be the main underlying feature. "Renin–angiotensin–aldosterone system (RAAS) blockers have also been found to be related to the risk of suicide due to the central role played by RAAS in mood disorders." (PMID 38399362, 2024). "used a large hospital database of 525,046 hypertensive patients from Scotland and revealed that patients taking CCBs had a higher risk of admission for mood disorders than patients taking renin-angiotensin system inhibitors at a 5-year follow-up." (PMID 38800057, 2024). "Targeting the brain renin-angiotensin system may also be a viable option for the treatment of mood disorders, cognitive dysfunctions and even neurodegenerative diseases." (PMID 21247419, 2011).
postural orthostatic tachycardia syndrome (5 papers, 2020 to 2025). A condition characterized by development of symptoms while standing. "Similarly, astronauts who maintain their blood volume and exhibit normal levels of renin, aldosterone, and norepinephrine, key regulators of fluid balance and vascular tone, may be less susceptible to post-flight orthostatic intolerance." (PMID 38681405, 2024). "In this study, we report a downregulation of renin activity in patients with postural orthostatic tachycardia syndrome (POTS) when compared to healthy controls." (PMID 37510775, 2023). "Potential biomarkers for resilience against orthostatic intolerance include normal heart rate variability (HRV) and normal circulating levels of renin, aldosterone, and norepinephrine." (PMID 38681405, 2024). "Early studies have found that children with postural orthostatic tachycardia syndrome (POTS) exhibit reduced blood volume, yet plasma renin and aldosterone levels do not increase accordingly, leading to the concept of the “renin-aldosterone paradox” in these patients." (PMID 40453223, 2025).